IL6 (interleukin 6)
Diseases named in the same sentence as IL6 in open-access papers (continued):
Sharing a sentence is not in itself a finding about the gene and the disease.
COVID-19 (continued). "In the circulation of patients with COVID-19, IL-6 reaches its peak at advanced stages, on average after the second week of disease, and, notably, this increase is accompanied by peak concentrations of IL-10 and CRP." (PMID 35340805, 2022). "Serum metabolic analyses of patients with COVID-19 have identified an altered tryptophan metabolism, and this change correlates with IL-6 levels." (PMID 35281455, 2022). "Here, we assess the relationship between IL-6 signalling variables [IL-6, soluble IL-6R (sIL-6R) and soluble gp130 (sgp130)] and outcomes in a cohort of 366 COVID-19 patients." (PMID 35634332, 2022). "Elevated serum levels of CRP, D-dimer, IL-6, LDH, and creatinine have been associated with disease progression and poor clinical outcomes in COVID-19 patients." (PMID 35160150, 2022). "In conclusion, increased CRP, IL-6, KL-6, HMGB-1, and d-dimer levels and decreased platelet counts were associated with the start of mechanical ventilation due to COVID-19." (PMID 35204430, 2022). "A meta-analysis of nine studies from China that studied 1426 patients supported the role of IL-6 in COVID-19 virulence." (PMID 35062368, 2022). "In patients with COVID-19, IL-6 levels correlate directly with fibrinogen levels, as well as with the increased levels of prothrombotic acute-phase reactants such as vWF, fibrinogen, and factor VIII." (PMID 35722697, 2022). "The high elevated levels of IL-6, IL-1 and TNF-ɑ have been associated with the increased monocytes and macrophages in the COVID-19 patients experiencing cytokine storm." (PMID 36094915, 2022). "Resistin was significantly associated with IL-6, IL-8, IL-10, VCAM-1 and ICAM-1 in the COVID-19 patients." (PMID 35784283, 2022). "Studies have shown that severe COVID-19 is accompanied by hypercytokinemia with high levels of pro-inflammatory cytokines such as IL-6 and IL-1β as well as anti-inflammatory cytokines such as IL-4 and IL-10." (PMID 35007290, 2022). "Higher mean IL-6 levels in COVID-19 deaths than in COVID-19 survivors were also reported by a previous meta-analysis." (PMID 35215138, 2022). "An interesting randomized controlled trial on forty COVID-19 patients supplemented with nano-curcumin showed a significant reduction in IL-1β and IL-6 expression and secretion." (PMID 35011106, 2022). "Multivariate logistic regression analyses of IL-6 signalling biomarkers as predictors of COVID-19 mortality." (PMID 35634332, 2022). "In particular, the plasma levels of some inflammatory proteins including tumor necrosis factor (TNF) and interleukin-6 (IL-6) were significantly increased in patients with severe COVID-19." (PMID 35283772, 2022). "From literature we know that IL-6, D-Dimer and fibrinogen levels are elevated in patients with COVID-19, indicating activation of coagulation pathways and a hypercoagulable state or thrombotic risk." (PMID 36131342, 2022). "Due to the inflammatory process in COVID-19, we believed it was essential to evaluate the outcome of inflammation reflected in the changes in interleukin-6 (IL-6) and insulin." (PMID 35530861, 2022). "Among the increased levels of inflammatory mediators in COVID-19 patients, the plasma levels of IL-6, an amplifier in the cytokine storm, are significantly elevated in non-survivors compared with survivors." (PMID 35222441, 2022). "We found that plasma exosomes from COVID-19 patients upon admission (E) significantly stimulated the production of cytokines and chemokines, including IL-6, IL-8, and TNF-α, compared with those from the same patients later in their hospitalization." (PMID 36526691, 2022). "The researchers also found oligozoospermia, leukospermia, and increased levels of interleukin-6 in some of the patients who had recovered from COVID-19." (PMID 36569699, 2022). "The NF-κB and JAK-STAT pathways are activated during COVID-19, which can initiate the IL-6 amplifier response, resulting in NF-κB hyperactivation." (PMID 36298501, 2022).
COVID-19 (continued). "Cytokine levels of IL-6 and IL-10, which are markedly increased in patients with COVID-19, can elicit the upregulation of NKG2A expression, potentializing its inhibitory role." (PMID 35806995, 2022). "The hyperinflammatory state in COVID-19 orchestrated by cytokines such as IL-6 is one of the mechanisms explaining the presence of impaired erythropoiesis." (PMID 36341268, 2022). "The significant risk factors of death related to COVID-19 were aging, loss of consciousness, the need for intubation and low O2 saturation, and high ranges of WBC, BUN, LDH, IL-6, pro-BNP, and HCO3, which are consistent with prior reports." (PMID 35592525, 2022). "Elevated interleukin-6 (IL-6), a mediator of cytokine release syndrome, has been demonstrated in severe COVID-19 patients." (PMID 36143101, 2022). "One of the hallmarks of severe COVID-19 is the low levels of type I interferons (IFNs) and overproduction of inflammatory cytokines or chemokines such as IL-6 and TNF2–5." (PMID 35022513, 2022). "Nivoi IL-6 su bili značajno viši kod pacijenata sa COVID-19 nego kod zdravih osoba (7,63 ± 6,30 naspram 5,54 ± 2,10, P=0,006)." (PMID 36381078, 2022). "We sub-classified our COVID-19 patients according to their IL-6 levels assuming 15 ng/mL as a cut-off value reflecting the 95th percentile of IL-6 distribution in the control group." (PMID 35064792, 2022). "As indicated, the REMAP-CAP trial tested three IL-6 inhibitors—sarilumab, tocilizumab, and anakinra—in COVID-19 patients who needed organ support." (PMID 36362912, 2022). "Inflammatory mediators such as IFN-γ, tumor necrosis factor (TNF), IL-2, IL-6, and IL-10 were also elevated in COVID-19 patients, and higher levels were reported in the severe cases." (PMID 35330388, 2022). "It appears that aberrant myelopoiesis continues after recovery from COVID-19, and IL-8 and IL-6 remain important mediators for the mobilization and expansion of STAT3 expressing M-MDSC." (PMID 35812392, 2022). "The increased interleukin 6 (IL-6):α1AT ratio reflecting the balance between pro- and anti-inflammatory mechanisms has been related to poor outcomes in COVID-19 ICU patients." (PMID 35632833, 2022). "Recent research has established that a calcium release-activated calcium channel inhibitor, such as auxora, can reduce the occurrence of COVID-19 death due to blocking the release of multiple pro-inflammatory cytokines, including IL-6." (PMID 36254081, 2022). "It has been assumed that cytokines IL-6, IL-17A, and TNF-α are the major players in the cytokine storm and biomarkers for acute respiratory distress syndrome and mortality in patients with COVID-19 and definite risk factors, for example, obesity." (PMID 35684003, 2022). "When bLf was used to treat COVID-19 patients, IL-6 levels had significantly reduced until the end of the study, and similarly, the same reductions had been observed in D-dimer serum and ferritin levels." (PMID 36419551, 2022). "Elevated levels of IL-6, IL-8, and IL-10 were associated with the disease severity of COVID-19, and elevated levels of IL-1β, IL-6, and IL-8 were related to the prognosis of COVID-19 patients, which could be used to evaluate COVID-19 patients' disease severity and prognosis." (PMID 35540724, 2022). "Longitudinal studies on proinflammatory cytokine trajectory in COVID-19 remain unexplored, in this study, we found elevated levels of IL-6 and IL-8 in CoV2+ individuals even after 5-months of the first detection of infection." (PMID 35812392, 2022). "The idea that ART can affect COVID-19 comes from the fact that it can inhibit the production of IL-1B, IL-6 and IL-8 by inhibiting NF-κB translocation in a dose-dependent manner in vitro." (PMID 35359702, 2022). "Similar to the findings of the literature, patients with fungal infections received immunomodulators against COVID-19 cytokine storm more frequently (higher regimen of corticosteroids and anti-IL6 monoclonal antibodies)." (PMID 36012869, 2022).
COVID-19 (continued). "Early respiratory improvement was also observed in patients with high level IL-6, but those with severe COVID-19 but low IL-6 didn’t show better health conditions after treating tocilizumab." (PMID 35505345, 2022). "The markedly elevated inflammatory cytokines at baseline indicate aberrant immune response among severe COVID-19 patients, and a variety of them such as IL-6 are involved in CRS, which correlates with pulmonary damage, multi-organ injury, and death." (PMID 35350784, 2022). "Although not differentially abundant when comparing cases with controls, pulmonary IL-6 was lower in the late inflammatory COVID-19 patient cluster." (PMID 34710339, 2022). "• IL-6 plays a main role in COVID-19 severity, while TNF-α and IL-1β trigger the NF-κB signaling pathway." (PMID 35422702, 2022). "The increased inflammatory cytokines such as TNF-α and IL-6 induce apoptosis and necrosis in T cells, which are reduced in COVID-19." (PMID 35408447, 2022). "IL-6 has already been described as an independent prognostic factor of COVID-19 severity and mortality." (PMID 35743825, 2022). "In the course of COVID-19, plenty of cytokines are released, among which interleukin-6 (IL-6) is the precise factor that stimulates hepcidin and ferritin syntheses." (PMID 35967872, 2022). "The percentage and counts of immune-suppressive monocytes (mo-MDSCs) identified as CD14+ HLA-DR− monocytes were higher than normal values in severe COVID-19+ patients, independently from the amount of IL-6, IL-1β, IL-17A, TGF-β, TNF-α and IFN-γ." (PMID 35508575, 2022). "The combination of RIB with IFN β-1b and Lopinavir–Ritonavir therapy is currently in clinical trials for treating SARS-CoV-2 infection, which has been shown to significantly alleviate the COVID-19 symptoms and suppress IL-6 levels in serum." (PMID 36177032, 2022). "COVID-19 Patients with cardiac injury have increased inflammatory markers, such as IL-6, lymphopenia, and higher counts of leukocytes and neutrophils." (PMID 36123740, 2022). "In COVID-19, critically ill patients showed significantly higher levels of IL-6, indicating that IL-6 was a strong predictor for disease severity and survival possibility." (PMID 36204639, 2022). "A massive pro-inflammatory profile mediated by IL-1β, IL-6, TNF and IFN-γ together with lower levels of IL-10 was a systemic hallmark of critically ill COVID-19 patients." (PMID 35720401, 2022). "In general, anti-IL6 agents appear to be effective against medium to severe cases of COVID-19, increasing CD8+ T-cell frequency and functionalities, preventing multi-organ failure, reducing inflammation levels, and, thus, reducing the risk of mortality." (PMID 36428847, 2022). "In the RECOVERY and REMAP CAP studies, the IL-6 antagonists were administered within 48 h of hospitalization, indicating that treatment with these agents early in the severe COVID-19 stage provides the most benefit." (PMID 35991665, 2022). "Ferritin was most increased in COVID-19, while other systemic inflammation biomarkers such as IL-6 and procalcitonin were highest in CAP-strep." (PMID 35660785, 2022). "As already noted, monoclonal antibodies blocking either IL-6 or binding of IL-6 to receptors have been used/tested successfully in the treatment of rheumatoid arthritis, many cancer types, and COVID-19." (PMID 35867145, 2022). "Particularly, the overproduction of interleukin-6 (IL-6) appears to play a prominent role in worsening the disease severity and increasing mortality in patients with COVID-19." (PMID 35343397, 2022). "Our study supports the previous work finding very high levels of IL-6 and IP-10 in the serum of patients who succumbed to COVID-19." (PMID 35273264, 2022). "Increased plasma levels of IL-6 have been documented in previous retrospective studies enrolling COVID-19 patients, suggesting a main role of IL-6 in the cytokine storm in COVID-19." (PMID 36362514, 2022).
COVID-19 (continued). "A meta-analysis involving nine COVID-19 studies showed that the increase of IL-6 was positively correlated with the severity of COVID-19." (PMID 36076167, 2022). "To date, there is still an unmet need for understanding of the electrophysiological impact of cytokine storm-induced IL-6 overactivation in COVID-19 patients." (PMID 35058480, 2022). "Consistent results were obtained from several studies where plasma levels of IL-6 were found to be increased in COVID-19 patients being higher in severe cases." (PMID 36035415, 2022). "On the other hand, it was established that IL-6 was a key player in homeostasis maintenance as well as a proinflammatory biomarker and strong COVID-19 predictor." (PMID 36680144, 2022). "There is evidence that the cytokine IL-6 plays an important role in the pathologic inflammatory response that triggers severe COVID-19, as high IL-6 concentrations in hospitalized COVID-19 patients are associated with a prognosis for more severe courses." (PMID 36366539, 2022). "Several studies have shown that serum levels of pro-inflammatory cytokines, particularly IL-6, are elevated in patients diagnosed with COVID-19." (PMID 36238306, 2022). "Interleukin-6 (IL-6) plays an important role in the progression of many diseases, including COVID-19." (PMID 35735559, 2022). "A small study has shown that ACE-inhibitors decrease IL-6 levels and peak viral load in COVID-19 patients which has led to a change in antihypertensive management in COVID-19 patients." (PMID 35548445, 2022). "These large-scale data revealed that the serum levels of IL-6, IL-10, IL-2R, TNF-α, IL-1β, IL-4, IL-8, and IL-17 are potential risk factors for severity and high mortality in COVID-19." (PMID 35237162, 2022). "Some host responses also differ in timing and magnitude, including the delayed type I interferon (IFN-α,β), increased proinflammatory cytokines like TNF-α and IL-6, and reduced immune regulation that have been detected in COVID-19 patients." (PMID 35634338, 2022). "The primary goal of IL-6 antagonistic therapy is to decrease the need for advanced treatment in individuals with severe COVID-19." (PMID 36506506, 2022). "Increased levels of IL-6 were also reported in severe cases of COVID-19, impacting immune cell function and the antiviral mechanisms of immune cells." (PMID 36547597, 2022). "We also confirm the prediction value of antibody reactivity with SARS-CoV-2 N protein and the high serum levels of IL-6 in COVID-19 patients." (PMID 35386707, 2022). "This indicates that the elevated IL-6 values present in the serum of patients with COVID-19 are probably secreted by lung epithelial cells." (PMID 36551272, 2022). "Controversially, another study indicated that in severe COVID-19 cases, peripheral blood monocytes significantly increased expression of IL-6, TNF, IL-1β, and their receptors, as well as pro-inflammatory chemokines including CCL2, CCL3, and CCL4." (PMID 35632823, 2022). "Since NRF2 expression levels are low in the COVID-19 spectrum, high IL-6 expression is expected in these groups." (PMID 36377893, 2022). "Here, we report a recently immunized patient (BBIBP-CorV–inactivated vaccine) with coronavirus disease-2019 (COVID-19) and ANE, who had extremely high interleukin-6 (IL-6) level and Ran Binding Protein 2 (RANBP2) missense mutation (The first case in COVID-19)." (PMID 35870896, 2022). "TLR4-mediated production of IL-6 and TNF-α is associated with the severity of COVID-19 in patients with cardiometabolic comorbidities." (PMID 35356515, 2022). "Insulin resistance is induced by interleukin-6 (IL-6), affecting insulin receptor and substrate-1 phosphorylation, common in COVID-19 patients." (PMID 35729170, 2022). "In the primary infection COVID-19 patient cohort, several plasma proteins increase with COVID-19 disease severity, including IL-6, IL-8, IL-10, IL-4, and VEGF." (PMID 36679852, 2022).
COVID-19 (continued). "Overexpression of cytokines (IFN-γ, IL-1β, IL-2, IL-4, IL-6, and IL-10) have been observed in COVID-19 patients." (PMID 35168674, 2022). "Many studies have pointed to IL-6 as a crucial signature of the cytokine storm in severe COVID-19 patients." (PMID 35672716, 2022). "The results of the present study showed that in the plasma of COVID-19 patients, the expression of pro-inflammatory cytokines—TNFα and IL-6 and the anti-inflammatory interleukin—IL-10 increases, especially in the plasma of recovered COVID-19 patients." (PMID 36233111, 2022). "In 584 COVID-19 patients, the IL-6 levels showed an increasing trend with increasing disease severity, it is worth noting that the IL-6 values were concentrating in normal level in mild COVID-19 patients, while it was markedly increasing in critical patients." (PMID 36403042, 2022). "Compared to NI subjects, COVID-19 patients had significantly elevated levels of IL-6, IL-10, IFN-γ, CCL5, CXCL9, and CXCL10 and decreased levels of CXCL8." (PMID 36287506, 2022). "According to our best knowledge, this is the first study that assesses the concentration of FLCs and IL-6 in relation to specific SARS-CoV-2 antibodies in COVID-19 as well as healthy people." (PMID 36232891, 2022). "In the moderate group of COVID-19 patients, ROC analysis indicated that AUC were 0.656, 0.843, 0.735, 0.806 for IL-6, TXA2, NF-κB p50 and NF-κB p65 with sensitivities of 100, 88, 80, and 80%, and with specificities of 50, 75, 56, and 67% respectively." (PMID 36298501, 2022). "Studies have shown that IL-6, a proinflammatory cytokine increased in COVID-19 patients, inhibits the expression and activity of hepatic CYP isoenzymes, resulting in increased levels of drugs such as HCQ, CQ and remdesivir." (PMID 35359702, 2022). "Infection with COVID-19 causes a “cytokine storm” with increased CRP and IL-6, and these predict disease severity and poorer outcomes." (PMID 36614901, 2022). "Third, sustained high serum levels of several biomarkers of inflammation (IL-6, ferritin, CRP), coagulation and fibrinolysis (D-dimer) and tissue damage (LDH) are associated with poor COVID-19 prognosis across critically ill patients." (PMID 35995830, 2022). "Within COVID-19 patients, serum IL-6 and IL-10 levels, which were found to be predictive of disease severity, are significantly higher in critical group than in moderate and severe group." (PMID 36406394, 2022). "Univariate logistic regression analyses of IL-6 signalling components as predictors of COVID-19 mortality based on proposed scores." (PMID 35634332, 2022). "The minimum peak of COVID-19 viral load was documented at day 12 from symptom onset; it matched with the minimum values of IL-6 and ferritin, and the peak of D-dimer." (PMID 36685564, 2022). "It was demonstrated that within the cytokine storm, severe COVID-19 progresses with a significant rise in IL-6 levels." (PMID 35887600, 2022). "Levels of IL-8 more reliably predict the overall clinical COVID-19 disease scores at different stages than IL-6 levels; therefore, IL-8 has been suggested as a biomarker for the severity and prognosis of COVID-19 cases." (PMID 36428847, 2022). "Compared with moderate correlation between CRP and IL-6 observed in COVID-19 patients, the correlations of NP levels with either CRP or IL-6 were weak." (PMID 35529699, 2022). "Blood levels of pro-inflammatory cytokines IL-6, IL-17, and IL-8 were markedly elevated in severe COVID-19 patients, together with elevated macrophage and neutrophil activity." (PMID 35432324, 2022). "We observed that COVID-19 patients with increased levels of pGSN/IL-6, pGSN/HGF and pGSN/IgM compared with the other markers are more likely not to progress to severe disease and will eventually be discharged alive." (PMID 36148234, 2022).